LINC01594 (long independently transcribed non-coding RNA 1594)
Synonyms: TCONS_l2_00015893
Gene: Long non-coding RNA gene on chromosome 2 (108,167,125 to 108,217,886, reverse strand). Ensembl gene ENSG00000225328.
Diseases named in the same sentence as LINC01594 in open-access papers:
LINC01594 is named in the same sentence as 3 diseases in open-access papers, as found by Europe PMC text mining. Sharing a sentence is not in itself a finding about the gene and the disease.
LINC01594 shares sentences with these, for which no sentence is quoted: adenoma (1 paper); carcinoma (1); dysplasia (1).